MMP9 (matrix metallopeptidase 9)
Diseases named in the same sentence as MMP9 in open-access papers (continued):
Sharing a sentence is not in itself a finding about the gene and the disease.
endometriosis (continued). "The lower expression of TIMPs in endometriosis means that less MMP-9 is degraded, and EEECs are much more prone to migration." (PMID 26289107, 2015). "The aim of these assays was to establish a new signaling pathway in which up-regulation of MMP-9 via activation of OPN induced by estrogen correlates with the migration of endometrial epithelial cells in endometriosis." (PMID 26289107, 2015). "MMP-2 and MMP-9 have been found to be significantly increased in endometriosis patients versus controls." (PMID 26240814, 2015). "The expression levels of OPN and MMP-9 in normal EECs (NEECs) were inferior to those in EECs from patients with endometriosis (EEECs)." (PMID 26289107, 2015). "To compare the quantitative differences in OPN and MMP-9 expression levels in NEECs and eutopic EECs with endometriosis (EEECs), we performed real-time RT-PCR and western blots." (PMID 26289107, 2015). "Treatment with PKF 115–584, a small-molecule antagonist of the Tcf/β-catenin complex, decreased the amount of total MMP-9 approximately 75% in epithelial cells and 85% in stromal cells in patients with endometriosis." (PMID 26056600, 2014). "Treatment with PKF 115–584 decreased the amount of total MMP-9 approximately 75% in epithelial cells and 85% in stromal cells in patients with endometriosis." (PMID 23626717, 2013). "An immunohistochemical study revealed that MMP-9 expression is higher in endometriosis than proliferative endometrium." (PMID 23843796, 2013). "The aim of this study was to explore the effect of a traditional Chinese medicine (Xiaochaihu Tang, XCHT) on the expression of matrix metalloproteinase-2 (MMP-2) and MMP-9 in rats with endometriosis (EMs)." (PMID 24255667, 2013). "Treatment with PKF 115–584 inhibited MMP-9 activity to undetectable levels in both menstrual endometrial epithelial and stromal cells of patients with endometriosis." (PMID 23626717, 2013). "MMP-2 and MMP-9, by degrading extracellular cellular matrix and promoting the release of key factors, play a critical role in the pathogenesis of endometriosis." (PMID 23843796, 2013). "Several reports have indicated that melatonin regulates the activity of MMP-9 during protection against ethanol-induced gastric ulcer and endometriosis." (PMID 21167057, 2010). "Endometriosis is associated with elevated levels of MMP-9 regardless of the biological compartment studied." (PMID 40810077, 2025). "Further, MMP9 expression was the lowest in the endometriosis group of patients." (PMID 41272701, 2025). "Ongoing research is elucidating the molecular processes of NGAL and MMP-9 interactions in endometriosis, potentially facilitating their integration into individualized treatment regimens and disease monitoring, thereby enhancing endometriosis management." (PMID 40810077, 2025). "The Steroid Receptor Coactivator-1 (SRC-1) isoform/Matrix Metalloproteinase-9 (MMP-9)/Estrogen Receptor beta (ERβ) axis has been identified as a key driver of endometriosis by inhibiting apoptosis and promoting inflammatory responses within endometriotic lesions." (PMID 40951281, 2025). "Both the current meta-analysis and bioinformatics analysis indicate differences in MMP-9 concentration levels between endometriosis patients and healthy individuals, with potentially elevated MMP-9 concentrations in serum samples from patients with endometriosis." (PMID 39544239, 2024). "Subgroup analysis based on different stages of endometriosis revealed a trend towards significantly higher serum MMP-9 concentrations in patients, whether in stages I-II or III-IV." (PMID 39544239, 2024). "This discovery suggests that MMP-9 could serve as a potential biomarker for distinguishing endometriosis from other conditions." (PMID 39544239, 2024). "MMP-2 and MMP-9 are the key factors of endometriosis progression and pathogenesis." (PMID 38255200, 2024).
endometriosis (continued). "Therefore, we performed a subgroup analysis that showed higher concentrations of MMP-9 in patients with endometriosis (EMT) compared to patients with uterine fibroids, patients with other diseases, and healthy individuals." (PMID 39544239, 2024). "Furthermore, stress-induced phosphoprotein-1 (STIP-1), an adaptor protein for Hsp70 that is up-regulated in the circulation of patients with endometriosis, is known to regulate cell migration via matrix metalloproteinase 9 (MMP-9) and metastasis." (PMID 39519195, 2024). "Moreover, the expression of MMP-2 and MMP-9 has been shown to be increased in women with endometriosis when compared to controls." (PMID 36901866, 2023). "Moreover, it has been found that overexpression of HOXA11-AS increases the membrane levels of CD44 and decreases the expression of matrix metalloproteinase-2, MMP-9, and vascular endothelial growth factors that are dysregulated in endometriosis." (PMID 35054341, 2022). "Moreover, the increased expression and activity of MMPs such as MMP2, MMP3, and MMP9 has been reported in endometriosis." (PMID 36551177, 2022). "Also, it was demonstrated that the expression of MMP-2 and MMP-9 is overexpressed in the eutopic endometrium as well as the endometriotic lesions of patients with endometriosis." (PMID 35059465, 2022). "One important member of the MMPs family, MMP-9, is known to participate in both invasion and metastasis of various tumours, and potentially plays a crucial role in both occurrence and progression of endometriosis." (PMID 35273494, 2022). "Aberrant regulation of MMPs such as MMP2, MMP3, and MMP9 has been reported in endometriosis." (PMID 35453712, 2022). "In endometriosis lesions, curcumin inhibits MMP-9 expression and can attenuate TIMP-1 expression." (PMID 32244563, 2020). "MMP-9 expression in endometriosis patients was increased compared to the controls (p = 0.002)." (PMID 32498419, 2020). "Curcumin administration can decrease MMP-2, MMP-3 and MMP-9 in serum mice presenting endometriosis." (PMID 32244563, 2020). "This indicates a significantly higher activity of MMP-9 in patients with endometriosis." (PMID 33072202, 2020). "Furthermore, MMP-9 was able to promote angiogenesis, which is argued to be a key process in the pathogenesis of endometriosis." (PMID 32046116, 2020). "Previous studies reported that MMP2 expression is increased along with other proteases in the late secretory endometrium, and that the expression level of MMP9 is elevated in patients with endometriosis, suggesting that their endometrial tissue is inherently more invasive." (PMID 31324015, 2019). "Unsurprisingly, IL-34, VEGF, MMP-2 and MMP-9 were increased in the sera of the experimental endometriosis rats, which could be abrogated by STAT6 signaling blockage with AS1517499." (PMID 31727934, 2019). "In patients with endometriosis, elevated levels of MMP-9 mRNA in ectopic tissues might play an essential role in endometrial tissue invasion and its ability to be implanted in ectopic sites." (PMID 31037923, 2019). "Further, an IL-34 neutralizing antibody could attenuate CSF1R/JAK3/STAT6 activation and down-regulate VEGF, MMP-2 and MMP-9, eventually leading to suppression of the development of endometriosis in vitro." (PMID 31727934, 2019). "In light of these findings, MMP-9 could be involved in the tissue growth and breakdown cycle that occurs during endometriosis, thereby potentially affecting the migration and dissemination of endometrial cells outside the uterus." (PMID 29304094, 2018). "In addition, MMP-9 concentrations are higher in the plasma and peritoneal fluids of patients with endometriosis than in those of healthy women." (PMID 29304094, 2018). "In addition, the expression of matrix metalloproteinase (MMP)-2 and MMP-9 have been shown to be higher in women with endometriosis compared to healthy controls." (PMID 28264481, 2017). "The expression of several MMPs, especially MMP9, has been demonstrated in endometriosis." (PMID 27790149, 2016).
endometriosis (continued). "Based on the findings above, we hypothesize that OPN might up-regulate MMP-9 expression as a result of the locally increased concentration of estrogen, which promotes the migration of endometrial cells and eventually leads to endometriosis." (PMID 26289107, 2015). "The present study suggests that the up-regulation of MMP-9 via activation of OPN induced by estrogen may correlate with the migration of endometrial epithelial cells in patients with endometriosis." (PMID 26289107, 2015). "In addition, MMP-2 and MMP-9 are elevated in the urine of patients with endometriosis compared to control." (PMID 23843796, 2013). "MMP-9 mRNA expression in epithelial cells prepared from menstrual endometrium was significantly higher than that from endometrium in other phases in patients with endometriosis." (PMID 23626717, 2013). "For example, the expression levels of MMP-2 and MMP-9 were higher in women with endometriosis." (PMID 23843796, 2013). "Furthermore, treatment with PKF 115–584 decreased the amount of active MMP-9 to undetectable levels in both epithelial and stromal cells of patients with endometriosis." (PMID 23626717, 2013). "Thus, we investigated whether PCB126 exposure modulates the SRC-1 isoform/MMP-9/ERβ axis in endometriotic lesions, thereby enhancing endometriosis progression." (PMID 40951281, 2025). "We note that a therapeutic approach to reduce MMP-9 level through progesterone supplementation to improve IVF success rates in endometriosis patients showed promising success, suggesting that MMP-9 may have treatment as well as diagnosis value in endometriosis." (PMID 38341605, 2024). "Thus, we may suppose that MMP-2 and MMP-9 are less suppressed in endometriosis patients, which, in turn, can lead to active migration (cell invasion)." (PMID 38255200, 2024). "Therefore, we sincerely hope that forthcoming research will accurately measure MMP-9 concentrations in the serum of endometriosis patients during both proliferative and secretory phases, categorizing them accordingly, to delve deeper into their pathophysiological mechanisms." (PMID 39544239, 2024). "Thus, the aims of this study were to first to examine VEGF and MMP-9 expression from endometriotic implants in rats with endometriosis and second to investigate the effects of metformin on endometrial receptivity through regulation of LIF and HOXA10 expression." (PMID 35273494, 2022). "Thus, an altered PR-A/PR-B ratio may impact the expression level of MMP-9 through the regulation of NF-κB activity, which could be important in the pathogenesis of endometriosis." (PMID 31037923, 2019). "In summary, our data suggest a potential role of STIP1 in endometriosis susceptibility, which may occur through the modulation of MMP-9 functions in a fashion independent of several known signaling proteins, such as NF-kB, ERK, AKT, and JAK2." (PMID 29304094, 2018). "Furthermore, Eleng capsules may also lower serum levels of soluble intercellular adhesion molecule-1(sICAM-1) and MMP-9 in patients with endometriosis, suggesting effects upon cell adhesion, invasion and angiogenesis." (PMID 30402122, 2018). "The results of the current study validate the diagnostic significance of the MMP-9/NGAL ratio, suggesting that it may exceed CA-125 and other markers by offering a more direct evaluation of extracellular matrix remodeling and inflammatory processes associated with endometriosis." (PMID 40810077, 2025). "IL-2 and IL-27 collectively downregulate MMP-9 expression through the regulation of IFN-γ and IL-10, thereby influencing the invasiveness of endometriosis cells." (PMID 40565017, 2025). "Out of these, significant overexpression of MMP7, MMP9, MMP11, IGFBP5, and TIMP1 was observed at both gene and protein levels in adenomyosis as compared to endometriosis." (PMID 41272701, 2025). "T antigens found on MMP-9 and glycosyl pro-MMP-9 multimers interact with sera from individuals with endometriosis." (PMID 40565017, 2025).
endometriosis (continued). "MMP9 and MMP7 showed strong discrimination for adenomyosis vs. endometriosis [area under the curve (AUC) = 0.93] and co-existent cases (AUC = 0.97), respectively." (PMID 41272701, 2025). "MMP7, MMP9, MMP11, and TIMP1 were observed to be significantly upregulated in women with adenomyosis as compared to endometriosis." (PMID 41272701, 2025). "This study revealed a significant increase in the MMP-9/NGAL ratio in the endometriosis cohort compared with the control group and in the stage III/IV endometriosis group compared with the stage I/II group." (PMID 40810077, 2025). "Research has consistently demonstrated that women with endometriosis have higher levels of MMP-2 and MMP-9 expression in their blood, peritoneal fluid, and endometrium compared to healthy individuals." (PMID 38398530, 2024). "MMP-2 and MMP-9 genes express statistically significant increases in stages II, III, and IV of extragenital endometriosis." (PMID 38255200, 2024). "The relative level of MMP-9 mRNA expression increased statistically significantly by 3.2, 3.4, and 4.3-fold in the II, III, and IV stages of extragenital endometriosis, respectively, compared with the control." (PMID 38255200, 2024). "Inflammatory mediators, such as cytokines and growth factors, can also stimulate the production of MMP-2, MMP-9, and TGF-β1 in endometriosis." (PMID 38398530, 2024). "Since MMP-2 and MMP-9 can break down and inactivate KISS1, an increase of MMP activity in endometriosis can work through feedback to decrease KISS1 levels, additionally eliminating possible inhibiting effects of KISS1 on migration and invasion." (PMID 38255200, 2024). "In female patients suffering from endometriosis, resveratrol showed potential in reducing the invasiveness of endometriosis due to reduced expression of MMP-2 and MMP-9." (PMID 38612425, 2024). "Specifically, it was observed that the administration of RiDE in rats with endometriosis was able to restore MMP2 and MMP9 values to normal conditions." (PMID 38398530, 2024). "Further, TNFα–MMP9 (Matrix metallopeptidase 9) axis generates endometriotic steroid receptor hormone 1 (SRC-1) isoform, which plays a crucial role in endometriosis disease progression in mice." (PMID 36693853, 2023). "It has been reported that metformin treatment reverses endometriotic implants in a rat model of endometriosis, through increasing superoxide dismutase activity and tissue inhibitor of MMP-2, and decreasing VEGF expression and MMP-9." (PMID 35273494, 2022). "In another study, it was shown that eutopic endometrium and ectopic lesions of women with endometriosis had lower levels of TIMP-3 mRNA expression, while the MMP-9 mRNA level was solely enhanced in ectopic lesions." (PMID 36235740, 2022). "IL-33 perpetuates inflammation, angiogenesis, and lesion proliferation in endometriosis and promotes the invasiveness of HESCs through the ST2/MAPK/MMP-9 pathway activated by 17β-estradiol." (PMID 36428461, 2022). "The protein and mRNA expression of the vascular endothelial growth factor (VEGF), matrix metalloproteinase-9 (MMP-9), the endometrial receptivity markers, LIF and HOXA10, were measured in the endometrium of rats with endometriosis." (PMID 35273494, 2022). "Several studies have reported that the levels of MMPs are elevated in the ectopic tissue, peritoneal fluid, or sera of patients with endometriosis, especially MMP2 and MMP9." (PMID 34827737, 2021). "Interleukin (IL)-2 and IL-27 synergistically inhibit MMP9 expression by maintaining the balance of interferon (IFN)-γ and IL-10, thereby improving the invasive ability of endometriosis cells." (PMID 34827737, 2021). "The levels of angiogenin, CD105, ICAM-1, CXCL10, leptin, lipocalin-2, MMP-9, osteopontin, RBP4, PAI-1, ABP, CD31, TIM-2, and VCAM-1 were higher in the endometriosis group than in the control group." (PMID 34072419, 2021).
endometriosis (continued). "An animal study revealed naringenin potential against endometriosis by reducing expression of various endometriosis prognostic markers (TAK1, PAK1, VEGF, PCNA, MMP2, and MMP-9) in endometriotic lesions developed in rats." (PMID 33919512, 2021). "In our study, there was an increase in MMP-9 expression and a decrease in TIMP-1 expression in endometrial cells isolated from the menstrual blood of patients with endometriosis." (PMID 32498419, 2020). "This study showed that the expression of MMP-9 is directly related to the presence of endometriosis, while TIMP-1 expression is inversely related to endometriosis." (PMID 32498419, 2020). "High levels of MMP-2 and MMP-9 and low levels of TIMP-1 were related with low production of mature oocytes and subsequent decreased quality of embryos in endometriosis patients who underwent in vitro fertilization (IVF)." (PMID 31037923, 2019). "In serial sections obtained from the same tissues, both epithelial and stromal cells of endometriosis/adenomyosis expressed STIP1 and MMP9." (PMID 29304094, 2018). "Both epithelial and stromal cells in surgical tissues of endometriosis and adenomyosis expressed STIP1 and MMP-9." (PMID 29304094, 2018). "As observed when LXA4 was administered on D−1, IL-1β, COX-2, VEGF, MRP4, TGF-β1, TGF-β2, CYP19a1, ERα, GREB1 and c-Myc expression were significantly attenuated whereas MMP-9 and TGF-β3 were upregulated in endometriotic lesions in established endometriosis." (PMID 24587003, 2014). "In a mouse model of endometriosis, PCB-126 exposure significantly promoted the growth of ectopic lesions by activating the Steroid Receptor Coactivator-1 (SRC-1) isoform/Matrix Metalloproteinase-9 (MMP9)/Estrogen Receptor-β (ERβ) axis, a key driver of disease progression." (PMID 40470214, 2025). "This review indicates that MMP-9 levels are consistently elevated in endometriosis across all investigations and irrespective of the biological compartment examined." (PMID 40810077, 2025). "Studies have shown increased activity of MMP-2 and MMP-9 in the endometrial tissue of women with endometriosis compared to that of women without endometriosis." (PMID 40429279, 2025). "Metformin treatment of endometriosis has been used, which decreases the expression levels of critical inflammatory and angiogenesis-related genes including VEGF, MMP2, and MMP9, while stimulating tissue inhibitors of metalloproteinase, endometrial stromal cells, and progesterone receptor expression." (PMID 40650261, 2025). "Despite numerous studies and suggested markers, only four biomarkers were identified as having strong potential for diagnosing endometriosis: tumor necrotic factor α (TNF-a), matrix metalloproteinase-9 (MMP-9), tissue inhibitor of matrix metalloproteinase 1 (TIMP-1), and microRNA-451 (miR-451)." (PMID 39768606, 2024). "Significantly higher levels of plasma MMP2 (p = 0.008), MMP9 (p = 0.001), and TGF-β1 (p = 0.053) were determined in the CTRL group when compared with the SHAM group (day 0), supporting the successful induction of endometriosis in rats." (PMID 38398530, 2024). "It has been suggested that deviating levels of MMP-2, MMP-9, and TIMP could contribute to the development of endometriosis." (PMID 38255200, 2024). "In this review, we observed that MMP-9 levels appeared to be increased in endometriosis in all studies and regardless of the biological compartment studied." (PMID 38341605, 2024). "We applied the quantitative polymerase chain reaction and the immunofluorescence method to investigate KISS1, its receptor (KISS1R), MMP-2, and MMP-9 in the eutopic and ectopic endometrium in women with and without endometriosis." (PMID 38255200, 2024). "Also, other factors can influence the levels of MMP-2, MMP-9, and TGF-β1 in endometriosis, including estrogen and progesterone, which are the primary sex hormones." (PMID 38398530, 2024).